SATB2 (SATB homeobox 2)
Diseases named in the same sentence as SATB2 in open-access papers (continued):
Sharing a sentence is not in itself a finding about the gene and the disease.
schizophrenia (15 papers, 2015 to 2025). A major psychotic disorder characterized by abnormalities in the perception or expression of reality. "SATB2 is a schizophrenia risk gene encodes a DNA-binding protein (Schizophrenia Working Group of the Psychiatric Genomics, 2014)." (PMID 37388494, 2023). "SATB2 is a schizophrenia risk gene encodes a DNA-binding protein (Schizophrenia Working Group of the Psychiatric Genomics, C., 2014)." (PMID 36590092, 2022). "Another gene set enrichment analysis showed that genes functionally related to or targeted by SATB2 are enriched for genes associated with schizophrenia." (PMID 36590092, 2022). "Genome-wide association studies show that common variants near and within SATB2 are mainly associated with brain and bone phenotypes, such as reaction time, anxiety, mathematical abilities, schizophrenia, autism, bone density, and facial morphology." (PMID 33885362, 2021). "Our data reveal a contribution of LEMD2‐regulated genes to human cognitive function and risk of schizophrenia and uncover a previously unexpected overlap of the human phenotypes that converge on gene sets controlled by SATB2 and LEMD2 in pyramidal neuron." (PMID 33319920, 2021). "We have recently shown that common variation in the genes regulated by SATB2 and in the genes encoding SATB2 protein interactors in the forebrain influence cognitive ability in the human general population and contribute to schizophrenia." (PMID 33319920, 2021). "SATB2 is associated with schizophrenia and is an important transcription factor regulating neocortical organization and circuitry." (PMID 30040823, 2018). "Interacting partners BCL11B and GATAD2A are also schizophrenia risk genes indicating that other genes interacting with or are regulated by SATB2 are making a contribution to schizophrenia and cognition." (PMID 30040823, 2018). "SATB2 is a risk locus for schizophrenia and encodes a DNA-binding protein that regulates higher-order chromatin configuration." (PMID 27897969, 2016). "Recent genome-wide association studies of schizophrenia have identified SATB2 as a genetic risk locus (Schizophrenia Working Group of the Psychiatric Genomics Consortium, 2014)." (PMID 27897969, 2016). "TOP2B2 peaks from untreated cells are associated with three genes (CNTN4, IMMP2L and SATB2) implicated in both autism and schizophrenia whilst TOP2B2 peaks from E2-treated cells are associated with five genes (CNTN4, IMMP2L, EPC, SMG6 and CACNA1C)." (PMID 26459242, 2015). "SATB2 is a schizophrenia risk locus and is associated with human cognitive ability." (PMID 33319920, 2021). "Satb2 is a genetic risk locus for schizophrenia and a regulator of several miRNAs responsible for the translation of proteins that control certain aspects of synaptic plasticity and memory formation: miR-124, miR-125b, miR-132, miR-212, miR-381, miR-326, and miR-19b." (PMID 34073140, 2021). "SATB2 is a schizophrenia risk gene and is genetically associated with human intelligence." (PMID 33319920, 2021). "Human SATB2 has also been identified as a risk locus for schizophrenia." (PMID 30726206, 2019). "Finally, about 10% of individuals with SAS have social affective behaviors and sensory issues, and Satb2 has been recognized as a risk gene for schizophrenia." (PMID 30809123, 2019). "Interestingly, amongst the miRNAs deregulated in Satb2-deficient CA1 we also found miRNAs shown to be deregulated in schizophrenia animal models or in schizophrenia patients." (PMID 27897969, 2016). "Schizophrenia GMV deficits in the hippocampus, temporal gyrus, and cerebellum are associated with genetic factors such as SATB2, GABBR2, and CACNA1C." (PMID 35717212, 2022). "Here we take an individual gene identified in a schizophrenia GWAS called SATB2, which on its own is a very important regulator of brain development." (PMID 30040823, 2018).
schizophrenia (continued). "This study provides evidence that the molecular mechanisms that underpin schizophrenia and cognitive function include disruption of biological processes influenced by SATB2 as the brain is being organized and wired during development." (PMID 30040823, 2018). "In this case we find evidence that genes influenced by SATB2 and involved in synaptic transmission, axon guidance and formation of the corpus callosum are contributing to schizophrenia and cognition." (PMID 30040823, 2018). "Consistent with this hypothesis, human genetic data reveal a contribution of both SATB2‐ and LEMD2‐regulated gene sets to human cognitive function and the risk of schizophrenia." (PMID 33319920, 2021). "Besides, a large number of genes are differentially expressed in Satb2 CKO mice, and some of them are risk genes associated with schizophrenia and other neurodevelopmental disorders." (PMID 30809123, 2019). "Of note, the reported schizophrenia risk allele for SATB2 (rs6704641) is intronic and likely affects SATB2 mRNA levels rather than protein function (Schizophrenia Working Group of the Schizophrenia Working Group of the Psychiatric Genomics Consortium, 2014)." (PMID 27897969, 2016). "At a mechanistic level, we establish Satb2 as a nuclear component of two main pathways implicated not only in cognition but also in schizophrenia pathophysiology, i.e. BDNF signaling and miRNA-mediated post-transcriptional regulation of gene expression." (PMID 27897969, 2016). "Meanwhile, interaction between SATB2 and the inner nuclear membrane protein LEMD2 alters expression of numerous genes that are related to schizophrenia etiology in pyramidal neurons." (PMID 36590092, 2022).
colon cancer (14 papers, 2012 to 2026). "Amongst the CDX2-correlated genes from human colon cancers, those downregulated in proximal organoids with Cdx2 loss included the key epithelial regulatory genes, such as Hnf4A, Satb2, and Vil1." (PMID 38360902, 2024). "Loss of tumor suppressor SATB2 is correlated with increased metastatic potential of colon cancer." (PMID 33572742, 2021). "K7 and TTF‐1 are the most sensitive and specific markers for identifying lung adenocarcinoma, while CDX2 and SATB2 are the most sensitive and specific markers for identifying colon cancer." (PMID 40309045, 2026). "Ectopic expression of SATB2 in colon cancer cells resulted in a decrease in ERK5 activation, colony formation, migration, and invasion in colon cancer cells and primary tumor growth in colon cancer xenografts in vivo." (PMID 33572742, 2021). "Immunostaining with CK7, CK20, CDX20, SATB2 is useful to distinguish the ductal tumor was a primary lesion or a metastatic lesion arising from colon cancer." (PMID 32975689, 2020). "Histological findings including the immune-histochemical examinations (CK7−, CK20+, CDX2+ and SATB2+) uncovered the metastatic tumor into extrahepatic bile duct originated from the primary colon cancer." (PMID 32975689, 2020). "Appendiceal tumors showed more positivity for SATB2 (77.8%) in comparison to colonic tumors (49.2%), making it a useful maker in discriminating POMNs from appendiceal and colonic tumors." (PMID 31771640, 2019). "SATB2 acts as a tumor suppressor in laryngeal squamous cell carcinoma and colon cancer, whereas SATB1 promotes the progression of numerous types of cancers." (PMID 26701851, 2016). "Furthermore, CDX2 and SATB2 are a highly sensitive and specific markers for metastatic lesions of gastrointestinal tract adenocarcinoma, especially colon cancer." (PMID 32975689, 2020). "The roles of SATB2 in colon cancer initiation, progression and metastasis are poorly understood." (PMID 28887549, 2017). "In conclusion, the findings from this large cohort study demonstrate that high SATB2 expression is an independent factor of good prognosis in colon cancer and imply a putative role for SATB2 in mediating increased sensitivity to chemotherapy and radiation therapy in CRC." (PMID 22333599, 2012). "High SATB2 expression is an independent marker of good prognosis in colon cancer and may modulate sensitivity to chemotherapy and radiation." (PMID 22333599, 2012). "Possibly, the lower, although non-significant, frequency of M1 tumours in rectal compared with colon cancers found here could in part explain the observed higher SATB2 expression in rectal cancer." (PMID 22333599, 2012). "High SATB2 expression was associated with a prolonged CSS in the full cohort (hazard ratio (HR)=0.61; 95% CI 0.41–0.92) and in colon cancer (HR=0.39; 95% CI 0.20–0.75), remaining significant in multivariable analysis of colon cancer (HR=0.49; 95% CI 0.25–0.96), with similar findings for OS." (PMID 22333599, 2012). "A highly significant inverse correlation was seen between SATB2 expression and MSI tumours in the full cohort and in colon cancer." (PMID 22333599, 2012). "Subgroup analysis according to location in patients with stage III-IV disease revealed a trend, however non-significant, towards an improved CSS and OS for SATB2 high tumours in colon cancer, which was not evident in rectal cancer (data not shown)." (PMID 22333599, 2012). "In colon cancer, the beneficial prognostic impact of high SATB2 expression (NS>9) was even more accentuated, whereas no prognostic value was seen for SATB2 expression in rectal cancer." (PMID 22333599, 2012).
breast carcinoma (13 papers, 2009 to 2025). "In breast cancer, SATB2 mRNA expression is significantly associated with increasing tumor grade and poorer survival." (PMID 28887549, 2017). "The characteristic immunophenotypic profile of CK7+/CK20- combined with GATA3+/CDX2- or GATA3+/SATB2- patterns provides definitive evidence supporting metastatic breast carcinoma to gastrointestinal sites." (PMID 40313249, 2025). "In this study, the expression profile of SATB1 and SATB2 is assessed in a cohort of women with breast cancer." (PMID 19642980, 2009). "In this study, the level of mRNA expression of SATB1 and SATB2 were assessed in normal and malignant breast tissue in a cohort of women with breast cancer and correlated to conventional clinico-pathological parameters." (PMID 19642980, 2009). "Similarly, significantly higher levels of SATB2 mRNA were found in the breast cancer specimens compared to the background tissue and expression was significantly associated with increasing tumour grade." (PMID 19642980, 2009). "SATB2 was found to be expressed in both normal/benign breast tissue and breast cancer specimens." (PMID 19642980, 2009). "However, another study from Pantani showed that the mRNA expression of SATB2 and SATB1 in human breast cancer were higher in malignant compared to normal breast tissue." (PMID 22815795, 2012). "Thus, we can speculate that GBK inhibits the migration and invasion of breast cancer cells by promoting the expression of miR-31, which in turn impaires the expression of miR-31 target genes, such as RHOA, WAVE3, and SATB2." (PMID 36313626, 2022). "Moreover, the expression of the miR-31 target genes SATB2 and RHOA was significantly reduced in SUM-159 cells after combination treatment with GBK and DDP, indicating that GBK could impair breast cancer cell migration and invasion." (PMID 36313626, 2022).
colorectal adenocarcinoma (13 papers, 2014 to 2025). The most common type of colorectal carcinoma. "Reduced expression of SATB2 has been associated with poor prognosis in colorectal adenocarcinoma, while in head and neck squamous carcinoma, the loss of SATB2 expression was associated with recurrence and high tumor grade." (PMID 38201285, 2023). "We also found some CD-SBNs showed SATB2 expression that is normally expressed in the large intestinal epithelium and considered a relatively specific marker for colorectal adenocarcinomas." (PMID 39164422, 2025). "In our case collections of gastrointestinal tumors, most cases with TTF-1 and/or Napsin A expression were CK20-positive and SATB2 expression was restricted to colorectal adenocarcinomas." (PMID 40564811, 2025). "The rectal cancer markers CK20 (+), CDX-2 (+), and SATB2 (+) are classic colorectal adenocarcinoma phenotypes, while CK7 (-), TTF-1 (-), and NapsinA (-) can exclude lung metastasis." (PMID 40837582, 2025). "Based on these results and the results of the tissue microarray from other common malignant lesions, researchers suggested that the combination of SATB2 with cytokeratin 20 (CK 20) is a highly specific marker for colorectal adenocarcinoma." (PMID 35055034, 2022). "Magnusson reported that 85% of colorectal adenocarcinomas expressed SATB2, but that expression was rare in pancreatic cancer and gastric adenocarcinoma." (PMID 28969003, 2017). "Cadherin-17 (CDH17) and SATB homeobox 2 (SATB2) immunoexpression have recently been demonstrated in colorectal adenocarcinoma." (PMID 28969003, 2017). "CDX2, CK7, CK20, and SATB2 were expressed in colorectal adenocarcinoma." (PMID 37608278, 2023). "For example, ZNF35 was found to differentiate the prognoses of COAD patients in a validation on independent test sets, and the transcription factor SATB2 was identified as a highly specific marker in colorectal adenocarcinoma when used in conjunction with CK20." (PMID 33202377, 2020). "The sensitivity of SATB2 in colorectal adenocarcinoma reaches 80%–97%." (PMID 28969003, 2017). "The SATB2 gene is involved in osteoblast differentiation and craniofacial patterning and has been demonstrated to be abundantly expressed in normal colorectal mucosa and colorectal adenocarcinomas, but more sparsely in other types of carcinomas." (PMID 25323550, 2014). "Histopathological examination revealed glandular structures resembling colorectal adenocarcinoma, with immunohistochemical positivity for CDX2, CK20, and SATB2, and negativity for TTF-1 and CK7." (PMID 41561768, 2025). "SATB homeobox 2 (SATB2) is the most sensitive and specific marker of colorectal adenocarcinoma and tumors with osteoblastic differentiation." (PMID 28969003, 2017). "The combination of CK7+/CDX-2+ was reported to have a high sensitivity (71.3%) and specificity (82%) in differential diagnosis of PEAC from colorectal adenocarcinoma, while combining cadherin-17 (negative) and SATB homeobox 2 (negative) also showed high sensitivity (77.0%) and specificity (100%)." (PMID 35172862, 2022). "Typically, primary colorectal adenocarcinomas are CK7-negative and strongly express CK20, CDX2, and SATB2.15,16) In our case, the intestinal tumors were negative for CK7 and CK20, with absent to weak CDX2 expression, and only weak SATB2 staining." (PMID 41159019, 2025).
developmental delay (13 papers, 2009 to 2025). "Rare mutations in SATB2 cause a syndrome that includes developmental delay, and mouse studies identify an important role for SATB2 in learning and memory." (PMID 30040823, 2018). "Haploinsufficiency of SATB2 is responsible for several of the clinical features such as craniofacial patterning, severe developmental delay and tooth abnormalities associated with 2q32q33 microdeletion syndrome." (PMID 25016475, 2014). "It has been suggested that haploinsufficiency of the SATB2 gene accounts for developmental delay, cleft/high arched palate, and possibly even the facial dysmorphism and psychiatric problems." (PMID 23840981, 2013). "Human patients with SATB2 haploinsufficiency suffer from severe neurological symptoms including cognitive deficits, developmental delay and absent/limited speech." (PMID 30726206, 2019).
gastric cancer (10 papers, 2016 to 2025). A primary or metastatic malignant neoplasm involving the stomach. "This concept is supported by the observation that a large proportion of TTF-1-positive colonic or gastric cancers also showed an immunohistochemical expression of at least one of the following markers: SATB2, CK20, FABP1, and Villin-1." (PMID 40564811, 2025). "SATB2 has also been found to be downregulated in certain gastric cancers where it may function as a tumor suppressor." (PMID 27186882, 2016). "The overexpression of Special AT-rich sequence-binding protein 2 (SATB2) diminishes ERK5 expression, thereby curtailing gastric cancer proliferation and migration." (PMID 38785963, 2024). "Downregulation of SATB2 in patients with GC was associated with shortened survival and, in the gastric cancer cell line MGC-803, the overexpression of SATB2 was able to repress ERK5 expression, while activation of ERK5 restored the SATB2-induced inhibition of proliferation and migration." (PMID 32326163, 2020). "In CRC and gastric cancer cells, ERK5 is repressed by the tumor suppressor SATB2, and constitutive activation of ERK5 restores the SATB2-induced inhibition of proliferation." (PMID 30901834, 2019). "ZJU-0430 original gastric cancer tissues positively expressed most gastrointestinal tract markers (CK20, CAD17, and CDX2), and negative expressed β-catenin and SATB2." (PMID 31367188, 2019). "In addition, the original GBC tumour showed negatively staining CDX2, and the original gastric cancer showed positive staining for CK20, CAD17, CDX2, and was negative for β-catenin and SATB2." (PMID 31367188, 2019).
Glass syndrome (10 papers, 2016 to 2026). "HI of SATB2 causes SATB2-associated syndrome (also termed Glass syndrome), whose features include small jaws, flat face and a friendly personality – again, traits that match the domestication syndrome." (PMID 37588924, 2022). "These genes are associated with recognizable syndromes such as (acampomelic) campomelic dysplasia (SOX9), cerebro‐costo‐mandibular syndrome (SNRPB), SATB2‐associated syndrome (Glass syndrome, SATB2), Catel‐Manzke syndrome (TGDS), TARP syndrome (RBM10), and Stickler syndrome (COL2A1, COL11A1)." (PMID 41077824, 2026). "SATB2-associated syndrome (SAS; OMIM #612313), also called Glass syndrome, is a rare multisystemic disorder caused by haploinsufficiency or dysfunction of the SATB2 gene (OMIM #608148), located on chromosome 2q33.1." (PMID 41153445, 2025). "SATB2-associated syndrome (SAS; Glass syndrome, OMIM 612313) is a multisystemic autosomal dominant disorder caused by a variety of different molecular alterations involving SATB2." (PMID 40225157, 2023). "Many studies have confirmed the contribution of SATB2 to CP both in non-syndromic and syndromic forms, causing Glass syndrome (OMIM #612313), Pierre-Robin sequence with or without ankyloglossia and cleft-associated intellectual disability." (PMID 26561393, 2016).
autism (8 papers, 2015 to 2025). Persistent deficits in social interaction and communication and interaction as well as a markedly restricted repertoire of activity and interest as well as repetitive patterns of behavior. "In addition, mutations spanning SATB2 have been reported in patients with neurodevelopmental disorders, including autism." (PMID 28166306, 2017). "In other brain regions, key autism susceptibility genes included FOXP1 (caudate and putamen), MEF2C and SATB2 (cortical plate), and TBR1 and NR4A2 (subplate)." (PMID 41279531, 2025).
epilepsy (8 papers, 2017 to 2024). A brain disorder characterized by episodes of abnormally increased neuronal discharge resulting in transient episodes of sensory or motor neurological dysfunction, or psychic dysfunction. "A single case of a de novo nonsense mutation in Satb2 has been described in individuals with cleft palate, osteoporosis, profound mental retardation, epilepsy, a jovial personality, and craniofacial dysmorphism including gum hyperplasia, mandibular hypoplasia, and anterior pointing incisors." (PMID 34073140, 2021). "The Satb2 deletions reduce the neuronal excitability and excitatory inputs in pyramidal neurons of CA1, which contributes to the suppression of epilepsy when PTZ is administered." (PMID 34073140, 2021).